PFKP (phosphofructokinase, platelet)
Diseases named in the same sentence as PFKP in open-access papers (continued):
Sharing a sentence is not in itself a finding about the gene and the disease.
hepatocellular carcinoma (10 papers, 2016 to 2024). A malignant tumor that arises from hepatocytes. "The DNA methylation of PFKP (phosphofructokinase platelet) was significantly upregulated in tumors, and the detection of hepatocellular carcinoma was highly accurate." (PMID 36404333, 2022). "In a recent example, TDP-43 was found to inhibit the miR-520 family in hepatocellular carcinoma, which in turn disinhibited the platelet isoform of phosphofructose kinase (PFKP)." (PMID 28952053, 2018). "In addition, PFKP levels are higher in hepatocellular carcinoma (HCC) as compared to normal hepatic tissues, which promotes HCC proliferation and contributes to the maintenance of HCC stemness." (PMID 38217030, 2024). "Among the eight mRNAs in the model, the up-expressions of TKTL1, KDELR3, PFKP, SLC2A1, and PGF in hepatocellular carcinoma were confirmed in previous experimental studies, while the over-expression of SAP30 in HCC was reported in an earlier computational study." (PMID 36362375, 2022). "TAT-activated regulatory DNA binding protein (TARDBP), which is highly expressed in hepatocellular carcinoma (HCC), regulates glycolysis by inducing the expression of the platelet isoform PFK1 (PFKP)." (PMID 37164974, 2023). "We obtained a prognostic signature including eight hypoxia genes (ENO2, KDELR3, PFKP, SLC2A1, PGF, PPFIA4, SAP30, and TKTL1) and further established a hypoxia-related prognostic ceRNA network including 17 lncRNAs, six miRNAs, and seven mRNAs for hepatocellular carcinoma." (PMID 36362375, 2022).
glioma (7 papers, 2015 to 2024). A benign or malignant brain and spinal cord tumor that arises from glial cells (astrocytes, oligodendrocytes, ependymal cells). "Phosphorylation of PFKP by AKT at Ser386 inhibits PFKP degradation and promotes aerobic glycolysis of glioma cells and tumor growth." (PMID 37143582, 2023). "Recently, we have reported that levels of activated nuclear β-catenin are positively correlated with glioma grades and that PFKP plays an instrumental role in EGFR activation-induced β-catenin transactivation in GBM cells." (PMID 36435833, 2022). "Our study demonstrates for the first time that VDAC2 is a critical regulator for the metabolic reprogramming of glioma cells through controlling the PFKP-mediated glycolysis." (PMID 30250190, 2018). "The homologous isoform PFKP of PFK1 can be phosphorylated by AKT at Ser386, which inhibits the degradation of PFKP and promotes aerobic glycolysis in glioma cells and tumor growth." (PMID 37143582, 2023). "A reduction in PFKP expression largely reduced EGFR activation-induced VEGF mRNA expression and its protein expression in glioma stem cells (GSCs), LN229, and U251 cells." (PMID 36435833, 2022). "We found that the protein levels of HK II, PFKP, and PKM2 were all downregulated time-dependently by silibinin in U87, U251, SHG-44, and C6 glioma cells." (PMID 32801360, 2020). "PFKP, the nearest protein-coding gene for PFKP-DT, has been reported to interact with VDAC2, thus regulating phenotypic reprograming and glucose metabolism of glioma stem cells." (PMID 38229597, 2024). "We selected seven glycolytic genes (HK2, PFKP, ALDOA, PGAM1, ENO1, ENO2 and PDK1) and confirmed their strong up-regulation under hypoxia by QPCR in seven GBM cell lines (five patient derived glioma stem-like cells and two adherent GBM cell lines)." (PMID 25932951, 2015).
Obesity (7 papers, 2009 to 2023). Accumulation of substantial excess body fat. "The downregulation of Phosphofructokinase, Platelet (PFKP), which catalyses fructose 6-phosphate to fructose 1,6-bisphophate, is intriguing given that elevated expression is associated with raised BMI and obesity in genome wide association studies." (PMID 31086124, 2019). "Elevated PFKP expression is known to be associated with increased body mass index (BMI) and obesity." (PMID 27187453, 2016). "The results demonstrated that genetic variation in KCNJ11, BDNF, PFKP, PTER and SEC16B were associated with SGA and support the concept that genetic factors associated with obesity and/or type 2 diabetes are more prevalent in those born SGA compared to those born AGA." (PMID 20712903, 2010). "Other GWA studies have reported variants in the proximity of INSIG2 and within PFKP as novel obesity gene loci, however, attempts to replicate the association for the INSIG2 variant have been inconsistent, which also appears true for variation in PFKP." (PMID 19245693, 2009). "Alongside transcriptional mitochondrial oxidative downregulation, we observed higher pyruvate levels in acquired obesity, accompanied by higher glycolytic phosphofructokinases (PFKM and PFKP) and LDHA protein levels." (PMID 33948567, 2021). "In race/ethnic-specific analyses, we identified a number of genes related to obesity (GNPDA2, ZNF664-FAM101A, PFKP, SAMD4A), glycosylation (GYPC, FUT10), and carbohydrate metabolism (GNPDA2, PFKP, SLC45A)." (PMID 28521775, 2017). "We have found associations (with p values less than 0.05) for SGA with the diabetes related SNP in KCNJ11 and the obesity related SNPs in FTO, PFKP, PTER, SEC16B and BDNF." (PMID 20712903, 2010).
lung adenocarcinoma (6 papers, 2020 to 2025). A carcinoma that arises from the lung and is characterized by the presence of malignant glandular epithelial cells. "Analyzing 566 The Cancer Genome Atlas samples alongside lung adenocarcinoma (LUAD)-specific microarray and single-cell sequencing data, we identified 109 cuproptosis-associated genes, of which C1QBP and PFKP emerged as key prognostic markers." (PMID 41041346, 2025). "We first performed immunohistochemical (IHC) staining for PFKP protein using a lung tissue microarray containing 98 lung adenocarcinoma samples." (PMID 39664584, 2024). "To investigate the expression pattern of PFKP in NSCLC, we analyzed two clinical lung adenocarcinoma (LUAD) datasets." (PMID 35641476, 2022).
ovarian carcinoma (6 papers, 2021 to 2025). A malignant neoplasm originating from the surface ovarian epithelium. "Results indicated that high SLC16A3 and PFKP expression in patients with advanced ovarian cancer was associated with poor PFS, and high SLC16A3 expression in patients with poor or moderate differentiation was associated with poor PFS or PPS." (PMID 34277429, 2021). "Currently, it has been found that RAD51 and PFKP, among others, undergo lactylation modification in ovarian cancer, and the lactylation modification of these proteins further enhances their resistance to platinum-based drugs in ovarian cancer." (PMID 41023769, 2025). "SLC16A3, PFKP, and PGK1, which were highly expressed in ovarian cancer tissues in two databases and associated with poor prognosis, were selected for further analysis." (PMID 34277429, 2021). "Kaplan-Meier plotter analysis indicated that among the highly expressed glycolysis genes, SLC16A3, HK2, GPI, PFKP, and PGK1, were closely associated with poor PFS, PPS, or OS in patients with ovarian cancer." (PMID 34277429, 2021). "For instance, two independent studies have shown that reduced PFKP expression can attenuate p-ERK1/2 levels in triple-negative breast cancer cell lines and ovarian cancer cell lines." (PMID 38982480, 2024).
liver cancer (5 papers, 2016 to 2024). An epithelial or non-epithelial malignant neoplasm that arises from the liver. "In fact, the role of PFKP in other cancer types such as breast and liver cancer has been reported." (PMID 27049827, 2016). "Studies have found that PFKP can promote reverse transcriptional activation of β-catenin, leading to the expression of ALDH1 in liver cancer stem." (PMID 36387165, 2022). "Then, we also explored the correlation between the expression of 11 ROS-related genes and TNM stages in liver cancer, and the findings showed that the expression of CDKN2D, G6PD, MSRA, OXSR1, PFKP, and STK25 was connected with TNM stages (P < 0.05)." (PMID 34795841, 2021).
prostate carcinoma (5 papers, 2020 to 2025). A carcinoma that arises from epithelial cells of the prostate gland. "We used an isogenic prostate cancer PC-3 cells and their acid-adapted PC-3AcT cells representing the Warburg phenotype with activated glycolytic activity by HK and PFKP activation but unchanged mitochondrial TCA cycle and OXPHOS." (PMID 40089067, 2025). "What’s more, both HIF-1α and PFKP expression were significantly reduced in prostate cancer received docetaxel treatment in vivo." (PMID 36536346, 2022). "In this study, we showed that docetaxel treatment led to a significant inhibition of cell proliferation in prostate cancer cells through PFKP-mediated glycolysis." (PMID 36536346, 2022). "Further analysis showed that Smad3 overexpression in prostate cancer cells could overcome the decreased HIF-1α and PFKP caused by docetaxel." (PMID 36536346, 2022). "Moreover, ectopic expression of Smad3 in prostate cancer cells could overcome the decreased HIF-1α expression and its target gene PFKP caused by docetaxel treatment." (PMID 36536346, 2022).
triple-negative breast carcinoma (5 papers, 2020 to 2026). An invasive breast carcinoma which is negative for expression of estrogen receptor (ER), progesterone receptor (PR), and human epidermal growth factor receptor 2 (HER2). "In triple-negative breast cancer (TNBC), knockdown of YBX1 inhibited the expression of glycolytic genes (ENO1, SLC2A6, LDHA, PFKP, PGAM1, and GPI) and downregulated the expression of EMT-related genes and tumor migration and invasion." (PMID 41507134, 2026). "Furthermore, we explored the relationship between PFKP mRNA levels and OS or RFS in triple-negative breast cancer patients by KM plotter database." (PMID 32470015, 2020).
brain tumor (4 papers, 2020 to 2023). "Depletion of PFKP successfully inhibited the growth of brain tumors derived from intracranially injected LN229/EGFRvIII cells at day 18 and prolonged the survival time of the mice." (PMID 36435833, 2022). "Consistence with these results, depletion of PFKP expression inhibited the growth of brain tumors in the group intracranially injected EGFR-expressing naïve LN229 cells." (PMID 36435833, 2022). "Our previous in vivo tumor xenograft experiments have revealed that PFKP is required for brain tumor growth." (PMID 36435833, 2022). "Depletion of PFKP significantly reduced the growth of brain tumors, and this effect was abrogated by reconstituted expression of WT rPFKP, but not by that of rPFKP Y64F mutant." (PMID 32195176, 2020). "In this study, we demonstrate that PFKP promotes EGFR activation-induced VEGF expression in HIF-1α-dependent and -independent manners in GBM cells, leading to enhanced blood vessel formation and brain tumor growth." (PMID 36435833, 2022). "In this study, we demonstrate that PFKP plays an instrumental role in EGFR activation-induced β-catenin transactivation in a PFKP Y64 phosphorylation-dependent manner, thereby regulating migration, invasion, and proliferation of GBM cells and brain tumor growth." (PMID 32195176, 2020). "Importantly, we showed that EGFR-phosphorylated PFKP Y64 has a critical role in AKT activation and AKT-mediated β-catenin S552 phosphorylation and subsequent β-catenin transactivation and promotion of tumor cell glycolysis, migration, invasion, proliferation, and brain tumor growth." (PMID 32195176, 2020).
breast tumor (4 papers, 2017 to 2025). "We analyzed PFKP expression patterns in 100 samples (normal, primary breast tumor, and metastasis) using quantitative real-time polymerase chain reaction (qRT-PCR), and survival analyses were performed." (PMID 40821334, 2025). "CCLE data displayed that cell lines from sarcoma had the highest level of PFKP, and the lowest level of PFKP was found in breast neoplasm cell lines." (PMID 37833332, 2023). "This study highlights PFKP as a novel candidate gene in the metastatic progression of breast tumors, which may have prognostic and therapeutic relevance in breast carcinogenesis." (PMID 40821334, 2025). "We examined PFKP and Ki67 expression using qRT-PCR in metastasis, primary breast tumors, and ANCTs." (PMID 40821334, 2025). "We identified 34 differentially expressed genes in metastatic breast tumors, with CCDC6, PKIA, UACA, and PFKP significantly upregulated (p < 0.05)." (PMID 40821334, 2025).
colon cancer (4 papers, 2022 to 2025). "Different from previous research results, we found that PFKP knockdown can induce colon cancer cells arrest at G1 phase." (PMID 37151384, 2023). "However, our results revealed that PFKP knockdown could not induce colon cancer apoptosis." (PMID 37151384, 2023).
colorectal cancer (4 papers, 2023 to 2025). A primary or metastatic malignant neoplasm that affects the colon or rectum. "A recent study in colorectal cancer also validates that PFKP is significantly overexpressed in cancer tissues and overexpression of PFKP contributes to the growth and invasion of cancer cells by regulating cell cycle progression." (PMID 38217030, 2024). "To determine the clinical significance of PFKP expression in colorectal cancer (CRC), we analyzed public databases." (PMID 37151384, 2023). "Among these, the expression levels of PFKP were significantly increased in corresponding adjacent normal (p=5.78e-05) and colorectal carcinoma tissue (p<2.2e-16) compared to colon normal tissues." (PMID 37151384, 2023). "However, the impact of PFKP expression on the progression of colorectal cancer (CRC) in patients remains unknown." (PMID 37151384, 2023). "However, the clinical effect and biological role of PFKP in colorectal cancer remain unclear." (PMID 37151384, 2023). "However, the biological function of PFKP remains unclear in colorectal cancer (CRC)." (PMID 37151384, 2023).
diabetes (4 papers, 2010 to 2022). "Associated cardiovascular diseases include diabetes (PDLIM5, HDAC4, and TLE1), cardiac development (PDLIM5) and myocardial aging (CASP12), hypertension (PFKP and TAB2), and intracerebral and intraventricular bleeding (RUNX1) and stroke (AXIN2)." (PMID 36620623, 2022). "The molecular understanding of PFK isoform selectivity, coupled with future studies of the pyrazolo-oxazepine scaffold, could open the door to selective activation of PFKM and PFKP, and the development of new pharmacological therapies for diabetes and cancer." (PMID 34320407, 2021).
non-small cell lung carcinoma (4 papers, 2020 to 2024). A group of at least three distinct histological types of lung cancer, including non-small cell squamous cell carcinoma, adenocarcinoma, and large cell carcinoma. "Phosphofructokinase platelet-type (PFKP) is a rate-limiting enzyme involved in glycolysis and is closely related to the progression of non-small cell lung cancer." (PMID 33619234, 2021). "Additionally, PFKP regulates long-chain fatty acid oxidation through AMPK to alleviate metabolic stress induced by glucose starvation in non-small cell lung cancer cells." (PMID 38965505, 2024). "In transformed non-small cell lung cancer cells, F-actin bundling spatially sequesters the E3 ligase TRIM21, thus reducing its substrate PFKP degradation and enhancing glycolysis." (PMID 38351096, 2024). "EGF-induced nuclear translocation of β-catenin was also largely inhibited by depletion of PFKP in LN229 GBM cells and A549 non-small cell lung cancer cells." (PMID 32195176, 2020).
pancreatic cancer (4 papers, 2019 to 2023). "For example, a new study reported that hyperglycemia could enhance glycolysis by increasing LDHA activity and HK2, PFKP expression to promote pancreatic cancer progression." (PMID 31889896, 2019). "We first assessed glycolysis-related proteins Glut1, Glut4, hexokinase I and II, PKM I and II (as well as their phosphorylated forms), PFKP, and LDHA in AdipoRon-treated pancreatic cancer cell lysates by western blot." (PMID 35121743, 2022). "In agreement with the in vitro results, EGCG reduced the levels of PFKP and PKM2 (p < 0.01 for both) in pancreatic tumor xenograft homogenates, obtained from mice treated with EGCG." (PMID 31590367, 2019). "Of note, silencing PFKP had a slight additive effect on the growth inhibitory effect of EGCG, suggesting that regulating glycolysis represents an important mechanism of EGCG in inhibiting pancreatic cancer cell growth." (PMID 31590367, 2019). "Taken together, these findings indicate that silencing PFKP function has a slight additive effect on the growth inhibitory response of EGCG in both cell lines, and suggest that regulating glycolysis represents an important mechanism of EGCG in inhibiting pancreatic cancer cell growth." (PMID 31590367, 2019).
acute lymphoblastic leukemia (3 papers, 2022 to 2025). Leukemia with an acute onset, characterized by the presence of lymphoblasts in the bone marrow and the peripheral blood. "For example, in T-cell acute lymphoblastic leukemia (T-ALL), PFKP stimulated T-ALL cell invasion by upregulating the expression of C-X-C chemokine receptor type 4 (CXCR4)." (PMID 37833332, 2023). "This includes a pro-survival activity of cyclin D3/Cdk6 activity attributed to its phosphorylation and inhibition of glycolytic enzymes, phosphofructokinase (PFKP) and PKM2, in T acute lymphoblastic leukemia (T-ALL) cells and other tumors with high expression of Cdk6." (PMID 35670764, 2022). "FBXO7 also regulates glycolysis through its interaction with phosphofructokinase-platelet (PFKP), a key substrate of CDK6 in some T-cell acute lymphoblastic leukemia (T-ALL) cells." (PMID 40534867, 2025).
cervical cancer (3 papers, 2023 to 2025). A primary or metastatic malignant neoplasm involving the cervix. "Notable findings include CD70, FANCD2, PFKP, MORN3, and LEF1, which exhibited strong causal associations and potential relevance in cervical cancer pathogenesis." (PMID 40817807, 2025).
Hyperglycemia (3 papers, 2019 to 2024). An increased concentration of glucose in the blood. "Pharmacological inhibition of HK1 and PFKP effectively prevents sustained inflammation related to hyperglycemia and promotes neutrophil clearance." (PMID 38049662, 2024). "Our recent study reported that overexpression of phosphofructokinase platelet type (PFKP) reduced podocyte injury in hyperglycaemia state." (PMID 38063077, 2024).
lymph node metastasis (3 papers, 2020 to 2023). "Of note, a high expression of PFK1 isoform PFKP is related to tumor size, histological grade, lymph node metastasis, and poor patient survival in NSCLC, which represents the most frequent cause of cancer death in 2020)." (PMID 35626081, 2022). "Multivariate Cox regression model adjusted by age, lymph node metastasis (LNM), T stage and pathological grade also reported that the level of PFKP could serve as an independent prognostic factor for patients with BC (P = 0.001, HR = 2.742, 95% CI 1.505 to 4.994)." (PMID 32470015, 2020).
oral cancer (3 papers, 2019 to 2023). "In oral cancer, regulation of PFKP expression promotes cell proliferation, migration, and invasion." (PMID 36339718, 2022). "Treatment with BME on oral cancer cell lines significantly reduced mRNA and protein expression levels of key glycolytic genes SLC2A1 (GLUT-1), PFKP, LDHA, PKM and PDK3." (PMID 31638999, 2019).
renal carcinoma (3 papers, 2016 to 2024). A carcinoma arising from the epithelium of the renal parenchyma or the renal pelvis. "Our data indicate that PFKP not only is required for metabolic reprogramming and maintaining cell proliferation, but also may provide us with a valid target for anti-renal cancer pharmaceutical agents." (PMID 27049827, 2016). "Since GLUT1 was the major glucose transporter in renal cancer cells, we investigated whether PFKP knockdown decreased GLUT1 expression." (PMID 27049827, 2016). "Moreover, the silencing of PFKP resulted in a reduction in PPP activity and nucleotide biosynthesis in renal cancer cells." (PMID 38673877, 2024).